IGF2BP3 (insulin like growth factor 2 mRNA binding protein 3)
Diseases named in the same sentence as IGF2BP3 in open-access papers (continued):
Sharing a sentence is not in itself a finding about the gene and the disease.
angiosarcoma (1 paper, 2020). A malignant tumor arising from the endothelial cells of the blood vessels. "Next, we assessed the association between IGF2BP3 expression and PD-L1 expression, which is a positive prognostic marker for angiosarcoma." (PMID 32293476, 2020). "Here, we examined 30 cases of angiosarcoma to determine whether IGF2BP3 could be a useful diagnostic marker by comparing its expression in various types of vascular lesions." (PMID 32293476, 2020). "Eight of 30 (26.7%) cases of angiosarcoma and two of five (40%) cases of epithelioid hemangioendothelioma were positive for IGF2BP3." (PMID 32293476, 2020). "One previous report showed that two of five cases (40%) of angiosarcoma were positive for IGF2BP3 in tissue microarray samples." (PMID 32293476, 2020). "We evaluated the expression of IGF2BP3 in malignant (angiosarcoma and epithelioid hemangioendothelioma [EHE]) and benign (hemangioma, granulation tissue cappilaries, and pyogenic granuloma) vascular lesions using immunohistochemistry." (PMID 32293476, 2020). "We found eight of 30 angiosarcoma cases were positive for IGF2BP3, compatible with the previous study showing two of five cases of angiosarcoma were positive for IGF2BP3 in tissue microarray samples (26.7% vs 40.0%, p = 0.54)." (PMID 32293476, 2020). "IGF2BP3-equivocal stains were also observed in angiosarcoma (17 of 30 cases, 56.7%) and EHE (two of five cases, 40.0%)." (PMID 32293476, 2020). "Among IGF2BP3-positive cases of angiosarcoma, two cases (25.0%) were PD-L1-negative and six (75.0%) were PD-L1-positive." (PMID 32293476, 2020). "Again, there was no statistical association between IGF2BP3 expression and PD-L1 expression among the angiosarcoma cases." (PMID 32293476, 2020). "IGF2BP3 staining was positive in eight of 30 angiosarcoma cases (26.6%)." (PMID 32293476, 2020). "IGF2BP3 might promote angiosarcoma or EHE cell invasion and migration via the same mechanisms." (PMID 32293476, 2020). "In angiosarcoma, IGF2BP3 expression was independent of age, gender, location, morphological pattern, prognosis, presence of metastatic foci, and PD-L1 expression." (PMID 32293476, 2020). "However, the utility of IGF2BP3 staining would be limited, because the majority of angiosarcoma and EHE cases are negative or equivocal for IGF2BP3." (PMID 32293476, 2020). "In contrast to angiosarcoma and EHE, benign vascular lesions were all negative or equivocal for IGF2BP3." (PMID 32293476, 2020).
bladder (1 paper, 2024). "Our findings provide a better knowledge of the epitranscriptional regulation mechanisms of SRD5A3 expression and the biological and epigenetic importance of m6A reader IGF2BP3 in bladder tumorigenesis." (PMID 39680264, 2024).
bone tumor (1 paper, 2024). "Notably, IGF2BP3 expression was undetectable in the aggressive GCTB, NRH_GCT1, mirroring the distinct molecular mechanisms governing aggressiveness in this bone tumor." (PMID 38561347, 2024). "By contrast, these findings indicate that the absence of the IGF2BP3-Myc positive feedback loop in this cell type, and other possible differences in post-transcriptional regulatory programs, may contribute to the differential response of this aggressive bone tumor to translation inhibitors." (PMID 38561347, 2024).
carcinoma in situ (1 paper, 2021). "In GSE15605 carcinoma in situ data, the overall trend was still negative correlated.; In addition, IGF2BP3 had the most significant correlation with VIRMA." (PMID 34737950, 2021).
celiac disease (1 paper, 2026). An autoimmune genetic disorder with an unknown pattern of inheritance that primarily affects the digestive tract. "For instance, we identified IGF2BP3 in connection with celiac disease, a protein previously linked to intestinal barrier function, along with several other proteins not yet associated with these diseases." (PMID 41724807, 2026).
cerebellar disorder (1 paper, 2025). Diseases that affect the structure or function of the cerebellum. "Additionally, exploring the impact of Igf2bp3 on overall cerebellar function could uncover its role in neurological health and disease, potentially leading to novel therapeutic approaches for cerebellar disorders." (PMID 40883822, 2025).
chordoma (1 paper, 2024). Chordomas are rare malignant tumors arising from embryonic remnants of the notochord in axial skeleton. "The circTEAD1/IGF2BP3/Yap1 mRNA RNA‐protein ternary complex not only bolstered the stability of Yap1 mRNA but also exerted a pivotal role in driving chordoma tumorigenesis." (PMID 38659080, 2024). "Furthermore, elevated circTEAD1 expression enhanced Yap1 mRNA stability by forming a circTEAD1/IGF2BP3/Yap1 ternary complex, which led to chordoma invasion and proliferation." (PMID 38659080, 2024). "However, contrary to the proposed mechanism, it was demonstrated that circTEAD1 could form a circTEAD1/IGF2BP3/Yap1 mRNA ternary complex in the cytoplasm to regulate chordoma proliferation and invasion through the Hippo signalling pathway." (PMID 38659080, 2024).
chronic kidney disease (1 paper, 2023). Impairment of the renal function secondary to chronic kidney damage persisting for three or more months. "IGF2BP3 was upregulated in renal tubular epithelium of various animal models and patients with chronic kidney disease." (PMID 36520532, 2023).
clear cell carcinoma (1 paper, 2022). "The expression of IGF2BP3 in EC tissues has been shown to be elevated compared to that in normal endometrial tissues, especially in endometrial serous carcinoma and clear cell carcinoma." (PMID 35676262, 2022).
congenital heart disease (1 paper, 2021). A heart disease that is present at birth. "IGF2BP3 and CASZ1 have key functions in cardiac development, since defects in these genes lead to congenital heart disease." (PMID 34895303, 2021).
epithelial dysplasia (1 paper, 2023). "Besides, the expression of IGF2BP3 was increased in epithelial hyperplasia, epithelial dysplasia and SCC (all P<0.05)." (PMID 36793593, 2023).
esophagogastric junction adenocarcinoma (1 paper, 2020). "In addition, SNPs of IGF2BP2 and IGF2BP3 has been proved to promote the lymph node metastasis of esophagogastric junction adenocarcinoma." (PMID 32514248, 2020).
Granuloma (1 paper, 2020). A compact, organized collection of mature mononuclear phagocytes, which may be but is not necessarily accompanied by accessory features such as necrosis. "Surprisingly, some pyogenic granuloma samples were equivocal for IGF2BP3." (PMID 32293476, 2020).
HbH disease (1 paper, 2024). "We can also develop drugs for the METTL16_ YTHDF3_ SLC5A3 pathway, such as agents designed to regulate METTL16 to reduce ROS and change the expression of IGF2BP3 to improve haemoglobin, which will provide a new direction for the treatment of HbH disease." (PMID 39088431, 2024). "Moreover, METTL16 possibly affects the expression of haemoglobin through IGF2BP3, which regulates the clinical phenotype of HbH disease." (PMID 39088431, 2024).
hemangioma (1 paper, 2020). A benign vascular lesion characterized by the formation of capillary-sized or cavernous vascular channels. "In contrast, hemangiomas (10 cases) and granulation tissue capillaries (12 cases) were all negative for IGF2BP3, and some cases of pyogenic granuloma (six of 14 cases) was scored as equivocal." (PMID 32293476, 2020). "The current study shows that benign vascular lesions, including hemangioma and granulation tissue, were negative for IGF2BP3." (PMID 32293476, 2020).
hypopharyngeal cancer (1 paper, 2022). Carcinoma, predominantly squamous cell, arising from the epithelial cells of the hypopharynx. "Currently, the expression and related functional mechanisms of IGF2BP3 in hypopharyngeal cancer have not been reported, and the study of IGF2BP3 in hypopharyngeal cancer may bring an important breakthrough to solve the bottleneck of clinical diagnosis and treatment." (PMID 36237306, 2022).
Infertility (1 paper, 2026). "Genetic ablation of Igf2bp3 results in spermatogenesis defects, leading to male sub-fertility or even infertility." (PMID 41350940, 2026). "Genetic ablation of mouse Igf2bp3 resulted in male subfertility or infertility, characterized by sperm developmental defects and histone retention." (PMID 41350940, 2026). "Phenotypically, we observed variations in fertility among individual Igf2bp3−/− male mice, ranging from sub-fertility to infertility, along with differences in sperm motility and sperm count." (PMID 41350940, 2026).
keratoacanthoma (1 paper, 2022). A dome-shaped, rapidly growing skin lesion composed of well differentiated squamous cells. "HSC-1 and HSC-5 cells have also been used to look at the expression of IGF2BP3 (Insulin Like Growth Factor 2 mRNA Binding Protein 3) as a biomarker to distinguish between cSCC and keratoacanthoma or to evaluate the role of CXCR7 expression in cSCC." (PMID 35646967, 2022).
lipoma (1 paper, 2023). A benign, usually painless, well-circumscribed lipomatous tumor composed of adipose tissue. "DD LPS displayed higher expression compared to the benign lipoma control, p = 0.0078, whereas WD LPS IGF2BP3 expression was not significant, p = 0.999." (PMID 37760460, 2023).
liposarcoma (1 paper, 2023). A usually painless malignant tumor that arises from adipose tissue. "We found IGF2BP3 to be uniquely associated with poor survival among well-differentiated/dedifferentiated liposarcoma, a common subtype of STS, suggesting its role as a novel prognostic biomarker in this disease." (PMID 37760460, 2023). "Preliminary data have suggested an association with IGF2BP3 expression among patients with well-differentiated/dedifferentiated liposarcoma (WD/DD LPS), a disease where molecular risk stratification is lacking." (PMID 37760460, 2023). "To confirm the binding specificity of the IGF2BP3 antibody, and validate the prognostic value of IGF2BP3 in future studies, we performed Western blotting of a human liposarcoma cell line, LPS2, following CRISPR-cas9 mediated IGF2BP3 knockdown." (PMID 37760460, 2023).
liver fibrosis (1 paper, 2024). "Utilising similar antibodies targeting IGF2BP3, Jag1, Notch1/3, and Hes1 as a therapeutic strategy in pre‐existing liver fibrosis models would enhance the translational value of these discoveries." (PMID 39113232, 2024). "IGF2BP3 cKO mice treated with CCl4 showed ameliorated liver fibrosis compared to their control littermates." (PMID 39113232, 2024). "Using three methods to demonstrate that HSC IGF2BP3 knockdown attenuates liver fibrosis—short hairpin RNAs (shIGF2BP3), the BETi JQ1, and IGF2BP3−/− mice—enhances the reliability of our results." (PMID 39113232, 2024). "This highlights IGF2BP3‐induced m6A modifications as promising targets for liver fibrosis amelioration." (PMID 39113232, 2024). "This study demonstrated that IGF2BP3 knockout reduces liver fibrosis by promoting HSC ferroptosis (FPT) and inactivating HSCs." (PMID 39113232, 2024). "HSC‐specific deletion of IGF2BP3 enhanced HSC FPT and impeded their activation, thereby reducing liver fibrosis through the IGF2BP3/Notch/Jag1 signalling pathway." (PMID 39113232, 2024). "This study linked IGF2BP3 depletion to Notch‐Jag1 signalling in HSC activation and liver fibrosis development." (PMID 39113232, 2024). "Thus, we identified IGF2BP3 as a novel regulator of liver fibrosis with significant translational potential for treating this condition." (PMID 39113232, 2024). "In conclusion, HSC‐specific silencing of IGF2BP3 mitigated liver fibrosis in vivo." (PMID 39113232, 2024). "Nevertheless, the role of insulin‐like growth factor 2 mRNA‐binding protein 3 (IGF2BP3), a reader gene mediating m6A modifications, in liver fibrosis remains unclear." (PMID 39113232, 2024). "IGF2BP3 cKO mice were utilised to investigate the role of IGF2BP3 in liver fibrosis." (PMID 39113232, 2024). "Developing specific antibodies against IGF2BP3 for future studies on liver fibrosis could significantly enhance the translational potential of our current findings." (PMID 39113232, 2024). "Furthermore, targeting the IGF2BP3/Notch/Jag1 signalling axis presents a promising therapeutic approach for treating liver fibrosis." (PMID 39113232, 2024). "Similarly, IGF2BP3 knockout inhibited liver fibrosis in the NASH mouse model." (PMID 39113232, 2024). "Our study suggests that knocking out IGF2BP3 promotes FPT of HSCs and inhibits their activation and proliferation, thereby preventing liver fibrosis progression." (PMID 39113232, 2024). "This study explored the role of IGF2BP3 in liver fibrosis and uncovered a novel signalling pathway and molecular mechanisms of FPT in liver fibrosis." (PMID 39113232, 2024).
lymphatic system cancer (1 paper, 2022). "We observed that IGF2BP2 and IGF2BP3 expression was markedly upregulated in the central nervous system (CNS), lung, gastric tract, head, neck, pancreas, and lymphatic system cancers." (PMID 36686749, 2022).
malignant mesothelioma (1 paper, 2021). A malignant neoplasm of the pleura or peritoneum, arising from mesothelial cells. "Furthermore, IGF2BP3 has been used as a differential diagnostic marker to distinguish malignant mesothelioma from reactive mesothelial hyperplasia." (PMID 35127504, 2021). "The knockdown of IGF2BP3 in malignant mesothelioma cells resulted in the suppression of cell proliferation with an increase in the proportion of cells in the G1 phase of the cell cycle." (PMID 35127504, 2021). "In conclusion, we found that IGF2BP3 promotes cell proliferation, a critical step in tumorigenesis, by suppressing the expression of p27 in malignant mesothelioma." (PMID 35127504, 2021). "IGF2BP3 functions as an oncoprotein in many human cancers; however, to our knowledge, this is the first study on the biological function of IGF2BP3 in malignant mesothelioma cells." (PMID 35127504, 2021). "We focused on the cell cycle assay to investigate the role of IGF2BP3 in cell proliferation in malignant mesothelioma." (PMID 35127504, 2021). "In this study, we conducted a functional analysis of IGF2BP3 in malignant mesothelioma cell lines and the regulation of downstream genes." (PMID 35127504, 2021). "IGF2BP3 siRNA was transfected into malignant mesothelioma cells to knock down IGF2BP3, and the efficiency of transfection was evaluated by western blotting and RT-PCR." (PMID 35127504, 2021). "This study highlights the potential of IGF2BP3 as a therapeutic target for the treatment of malignant mesothelioma." (PMID 35127504, 2021). "IGF2BP3 has been reported as a prognostic biomarker of malignant mesothelioma, and its reduced expression has a positive effect on life expectancy." (PMID 35127504, 2021). "We identified insulin-like growth factor 2 mRNA binding protein 3 (IGF2BP3) as one of the significantly upregulated genes in malignant mesothelioma." (PMID 35127504, 2021). "IGF2BP3 expression correlates with poor prognosis in malignant mesothelioma." (PMID 35127504, 2021). "There are a few studies on IGF2BP3 expression in malignant mesothelioma." (PMID 35127504, 2021).
malignant vascular neoplasm (1 paper, 2020). "Although sensitivity is not always high, IGF2BP3 can be a supplemental marker to recognize tumor cells in small biopsy specimens or tumor cut end for malignant vascular neoplasm." (PMID 32293476, 2020).
mantle cell lymphoma (1 paper, 2021). Mantle cell lymphoma is a rare form of malignant non-Hodgkin lymphoma affecting B lymphocytes in the lymph nodes in a region called the ``mantle zone''. "Increased expression of IGF2BP3 is associated with proliferative features in many solid tumors, mantle cell lymphoma, and chronic myeloid leukemia blast crisis, and promotes cell survival during ionizing radiation in B-cells." (PMID 33805930, 2021). "A high expression of IGF2BP3 has been associated with proliferative phenotype in malignancies such as mantle cell lymphoma." (PMID 33805930, 2021).
meningioma (1 paper, 2023). A generally slow growing tumor attached to the dura mater. "Overall, IGF2BP3 has been less studied in meningioma and may be a suitable predictor of recurrence in meningioma patients." (PMID 37298373, 2023).
metastatic prostate carcinoma (1 paper, 2020). A carcinoma that arises from the prostate gland and has spread to other anatomic sites. "Similarly, the previous study has reported that IGF2BP3 was highly expressed in metastatic prostate cancer patients and independently correlated to worse cancer-specific survival." (PMID 32710725, 2020).
Miscarriage (1 paper, 2022). A pregnancy that ends at a stage in which the fetus is incapable of surviving on its own, defined as the spontaneous loss of a fetus before the 22th week of pregnancy. "This suggests that IGF2BP3 may also regulate trophoblast invasion and migration by modulating cytokine communication (including TGF-β1) at the maternal–fetal interface in mouse models of miscarriage." (PMID 35465321, 2022).
myeloid leukemia (1 paper, 2024). A clonal proliferation of myeloid cells and their precursors in the bone marrow, peripheral blood, and spleen. "Notably, IGF2BP3 has been reported to stabilize Myc transcripts by cooperating with YBX1 in an N6-methyladenosine (m6A)-dependent manner in myeloid leukemia cells." (PMID 38561347, 2024).
oligoasthenoteratozoospermia (1 paper, 2026). A form of male infertility that is characterized by a combination of low number or oligozoospermia, poor motility or asthenozoospermia, and abnormal shape or teratozoospermia of sperms. "Collectively, male mice lacking IGF2BP3 displayed composite phenotypes resembling human oligoasthenoteratozoospermia." (PMID 41350940, 2026).
papillary thyroid carcinoma (1 paper, 2023). "All the THADA/IGF2BP3 fusion malignancies were a follicular variant of papillary thyroid carcinoma." (PMID 37444504, 2023).
peritoneal neoplasm (1 paper, 2021). A benign or malignant neoplasm that affects the peritoneal cavity. "IGF2BP3 was related to soft tissue neoplasms and peritoneal neoplasms." (PMID 34778266, 2021).
prediabetes (1 paper, 2023). "We aimed to explore IGF2BP3 serum levels and clinical characteristics in 113 T2DM patients, 124 age‐ and sex‐matched participants with prediabetes and 119 age‐ and sex‐matched healthy participants as controls." (PMID 36891946, 2023).
prostate tumors (1 paper, 2020). "All mRNA m6A regulators were detected on the mRNA level in prostate tumors and normal prostates except IGF2BP1 and IGF2BP3 which were excluded from subsequent analyses." (PMID 33273988, 2020).
pyogenic granuloma (1 paper, 2020). A disorder of the skin, the oral mucosa, and the gingiva, that usually presents as a solitary polypoid capillary hemangioma often resulting from trauma. "IGF2BP3-positive pyogenic granuloma might be associated with the presence of such mutations." (PMID 32293476, 2020).
renal fibrosis (1 paper, 2023). A final common manifestation of a wide variety of chronic kidney diseases characterized by glomerulosclerosis and tubulointerstitial fibrosis. "Overexpression of IGF2BP3 impairs kidney integrity and drives renal fibrosis via activation of β-catenin." (PMID 36520532, 2023). "Taken together, IGF2BP3 and β-catenin create a reciprocal activation loop that synergistically promotes the pathogenesis of renal fibrosis." (PMID 36520532, 2023). "Therefore, depletion of IGF2BP3 ameliorates renal fibrosis and inhibits β-catenin activation after UUO." (PMID 36520532, 2023).
rhabdomyosarcoma (1 paper, 2015). A rare aggressive malignant mesenchymal neoplasm arising from skeletal muscle. "IGF2BP3 protein could bind to IGF2 mRNA and promote IGF2 protein expression in human rhabdomyosarcoma cells." (PMID 26327240, 2015).